LILRB1 (leukocyte immunoglobulin like receptor B1)
Diseases named in the same sentence as LILRB1 in open-access papers (continued):
Sharing a sentence is not in itself a finding about the gene and the disease.
glioma (5 papers, 2022 to 2025). A benign or malignant brain and spinal cord tumor that arises from glial cells (astrocytes, oligodendrocytes, ependymal cells). "In the present study, we discovered that LILRB1 was markedly increased in glioma and was identified as a standalone risk factor for glioma." (PMID 37142967, 2023). "Last but not least, the MRI images confirmed that an elevated expression of LILRB1 was linked with a bigger tumor volume and a longer spread distance in patients with glioma." (PMID 37142967, 2023). "In accordance with the results in the TCGA portal and CGGA database, LILRB1 was upregulated in glioma tissues and positively associated with tumor progression and poor prognosis in our 38 clinical samples." (PMID 37142967, 2023). "In the same manner, we also found that to enhance development of glioma, a higher LILRB1 expression was implicated in the regulation of the B cell receptor signaling pathway, chemokine signaling pathway and Toll-like receptor signaling pathway." (PMID 37142967, 2023). "Understanding the underlying functions of LILRB1 in the glioma formation and progression will be improved by the identification of associated genes." (PMID 37142967, 2023). "Univariate and multivariate Cox regression analyses determined that increased LILRB1 expression was a standalone causal factor for glioma." (PMID 37142967, 2023). "Higher LILRB1 expression was considerably present in the higher WHO grade glioma group and was linked to a poorer prognosis in patients with glioma." (PMID 37142967, 2023). "Dysregulation of LILRB1 in glioma is correlated with immune infiltration and is a standalone causal factor for glioma." (PMID 37142967, 2023). "Finally, the MRI images demonstrated a positive association between high LILRB1 expression and a bigger tumor volume and a longer spread distance in patients with glioma." (PMID 37142967, 2023). "In addition, univariate and multivariate Cox regression analyses detected LILRB1 as a standalone causal factor for glioma." (PMID 37142967, 2023). "Furthermore, in our experiments, LILRB1 was abundant in tumor tissues of patients with glioma and increased levels of LILRB1 expression were strongly linked to a worse prognosis." (PMID 37142967, 2023). "In glioma, high LILRB1 expression correlated with increased tumor volume and independently predicted poor prognosis, confirming its role as a pathogenic driver." (PMID 40860159, 2025). "Undoubtedly, in our study, LILRB1 expression was found to be positively connected with TMB in glioma, while LILRB1 expression was adversely correlated with MSI." (PMID 37142967, 2023). "Similar to this, we confirmed in our study that increased LILRB1 expression was linked to increased infiltration of B cells, CD4+T cells, M2 macrophages, neutrophils, and dendritic cells in patients with glioma." (PMID 37142967, 2023). "We examined further at how LILRB1 affected the immunological microenvironment in patients with glioma." (PMID 37142967, 2023). "In our work, we demonstrated a favorable relationship between M2 TAMs infiltration and increased LILRB1 expression in patients with glioma." (PMID 37142967, 2023). "More in vitro and in vivo functional investigations are required to confirm the mechanistic significance of LILRB1 in the genesis and development of glioma." (PMID 37142967, 2023). "In order to achieve this, we used bioinformatics and vitro experiments to examine the predictive importance and potential biological roles of LILRB1 in glioma." (PMID 37142967, 2023). "Immunohistochemical staining of the 38 clinical samples confirmed a different level of LILRB1 expression in tumor tissues in different glioma grades and the LILRB1 expression increased with rising glioma pathological grade." (PMID 37142967, 2023). "In comparison to normal samples, the expression of the LILRB1 gene in glioma was significantly overexpressed." (PMID 37142967, 2023).
glioma (continued). "Further study using logistic regression analysis revealed a connection between increased LILRB1 expression and worse prognosis in patients with glioma." (PMID 37142967, 2023). "The PPI network of LILRB1 and related genes in glioma was created by Cytoscape, and the top 10 hub genes of LILRB1 discovered by the CytoHubba plugin were ranked in terms of the NCC score." (PMID 37142967, 2023). "We examined the data from the CGGA and TCGA databases to ascertain the link between LILRB1 and clinicopathological traits in patients with glioma." (PMID 37142967, 2023). "According to these findings, LILRB1 acts as an oncogene in glioma, and high expression of this gene predicts a poor prognosis." (PMID 37142967, 2023). "MRI images demonstrated that higher LILRB1 expression was related with larger tumor volume in patients with glioma." (PMID 37142967, 2023). "This investigation examined the immunological signature, clinicopathological importance and prognostic value of LILRB1 expression in glioma." (PMID 37142967, 2023). "We suggest that a higher LILRB1 expression would enhance glioma development by targeting the NOD-like receptor signal pathway." (PMID 37142967, 2023). "There was a strong connection between TMB and LILRB1, and an inverse relationship between MSI and LILRB1 in patients with glioma." (PMID 37142967, 2023). "Compared with low LILRB1 expression cases, glioma cases with high LILRB1 expression displayed greater volumes of peritumoral T2WI abnormality." (PMID 37142967, 2023). "In our vitro experiments, the CCK-8 assay demonstrated that LILRB1 positively turbocharged the proliferation in glioma cells." (PMID 37142967, 2023). "Using TCGA and the CGGA database, it was determined how LILRB1 expression affected the survival of patients with glioma." (PMID 37142967, 2023). "Vitro experiments determined that LILRB1 positively enhanced the proliferation, migration and invasion in glioma cells." (PMID 37142967, 2023). "Patients with gliomas that expressed a lot of LILRB1 had significantly lower survival times." (PMID 37142967, 2023). "LILRB1 is consequently connected to the emergence and spread of glioma." (PMID 37142967, 2023). "In addition, we performed survival curves for OS stratified by LILRB1 expression in glioma tissues derived from the 38 glioma samples." (PMID 37142967, 2023). "Combined with TMB and MSI, LILRB1 may be a promising predictor for the efficacy of immunotherapy in patients with glioma." (PMID 37142967, 2023). "Additionally, LILRB1 was overexpressed in glioma tissues in our sample of 24 paired tumor and peritumor tissues from patients with glioma." (PMID 37142967, 2023). "Taken together, LILRB1 may have a detrimental effect on the prognosis of glioma.by regulating the immune microenvironment." (PMID 37142967, 2023). "Therefore, we investigated the relationship between immune cells that have invaded glioma and LILRB1 expression." (PMID 37142967, 2023). "We establish that LILRB1 may be an oncogene and correlates with immune infiltration in glioma and may serve as a therapeutic target and prognostic indicator for glioma." (PMID 37142967, 2023). "Moreover, transwell assays determined that LILRB1 positively enhanced the migration and invasion in glioma cells." (PMID 37142967, 2023). "LILRB1 combined with tumor mutational burden (TMB) and microsatellite instability (MSI) may be a promising indicator for the effectiveness of immunotherapy in patients with glioma." (PMID 37142967, 2023). "Thus, we suggest that in combination with M2 TAMs, LILRB1 may promote tumor metastasis, invasion, angiogenesis, and tumor development in glioma." (PMID 37142967, 2023). "However, little is understood about LILRB1’s probable biological role in glioma." (PMID 37142967, 2023). "Nevertheless, we establish that LILRB1 corresponds with immune infiltration in glioma and may be an oncogene and connects with immune infiltration in glioma and may be a therapeutic strategy and prognostic indicator for glioma." (PMID 37142967, 2023).
glioma (continued). "Therefore, LILRB1 may be a standalone factor in glioma with poor prognosis." (PMID 37142967, 2023). "LILRB1 expression will affect the TME through M2 macrophages and may have a substantial effect on the immunological response of glioma." (PMID 37142967, 2023). "While neither a significant relationship with race nor gender was seen in the TCGA, elevated LILRB1 in our clinical glioma was highly connected with WHO grade and IDH." (PMID 37142967, 2023). "Similarly, in our study, LILRB1 was found to be substantially connected with prognosis, WHO grade, IDH status and 1p/19q codeletion in glioma." (PMID 37142967, 2023). "Similarly, LILRB1 was found in the highest grade glioma patients, and correlated with M2 macrophage markers, proliferation, migration and invasion of glioma cells, lack of response to immunotherapy and poor prognosis." (PMID 38022598, 2023). "We functionally annotated LILRB1 in our work using GO terms and KEGG pathways, and discovered that increased LILRB1 expression was positively connected with the JAK/STAT signaling pathway, indicating that LILRB1 would promote the development of glioma through the JAK/STAT signaling pathway." (PMID 37142967, 2023). "However, the importance of LILRB1 expression in glioma has not yet been determined." (PMID 37142967, 2023).
prostate carcinoma (5 papers, 2021 to 2025). A carcinoma that arises from epithelial cells of the prostate gland. "In prostate cancer, enhanced levels of LILRB1 mRNA were associated with a shorter biochemical recurrence-free survival according to prostate specific antigen levels in the blood." (PMID 37781391, 2023). "For example, in prostate cancer, a higher percentage of tumor infiltrating NK cells expressed LILRB1 in comparison to NK cells from control tissues." (PMID 37781391, 2023). "Tumor-induced upregulation of LILRB1 was supported further by subsequent findings revealing that certain tumor cells, i.e. prostate cancer cells and glioblastoma cells, are capable of inducing the expression of LILRB1 on NK cells in vitro." (PMID 37781391, 2023). "Interestingly, LILRB1 gene and protein levels correlate with a shorter progression-free survival and poor clinical outcome in high but not operated intermediate-risk prostate cancer patients, indicating its correlation with tumour grade." (PMID 38022598, 2023).
hepatocellular carcinoma (4 papers, 2023 to 2025). A malignant tumor that arises from hepatocytes. "Besides, LILRB1 is related to the pathologic progression of varieties of cancers like adenocarcinoma, hepatocellular carcinomas, pancreatic cancer, and so on." (PMID 37786523, 2023). "In hepatocellular carcinoma (HCC), LILRB1/LILRB2 suppress cytokine production by liver-infiltrating myeloid cells." (PMID 40821795, 2025). "Furthermore, LILRB1 CAR-T cells exhibited no cytotoxic effects against LILRB1-negative B-NHL cells as well as non-hematologic LILRB1-negative cells, such as breast and hepatocellular carcinoma cell lines." (PMID 40186066, 2025).
lymphoma (4 papers, 2019 to 2025). A malignant (clonal) proliferation of B- lymphocytes or T- lymphocytes which involves the lymph nodes, bone marrow and/or extranodal sites. "In a previous study, LILRB1 knock-in mice were established in the background of immune competent mice, but here immune deficient mice will be required to facilitate the engraftment of human lymphoma cells." (PMID 36389667, 2022). "For example, gene knock-down of β2m or antibody blockade of LILRB1 enhanced lysis of lymphoma cells by γδ T cell clones." (PMID 37781391, 2023). "The LILRB1 co-blockade promoted serial uptake of lymphoma cells, and demonstrated efficacy in both B-NHL cell lines and freshly isolated MCL or CLL cells from patients." (PMID 36389667, 2022). "Here, the impact of HLA class I expression on macrophage-mediated ADCP of lymphoma cells and the potential of antibodies blocking the cognate inhibitory receptors LILRB1 and LILRB2 was analyzed." (PMID 36389667, 2022). "In an effort to analyze the potential of LILRB1 and CD47 co-blockade to enhance the ADCP activity also of lymphoma-associated macrophages (LAM), MNC were prepared from BM samples from DLBCL patients with BM infiltration." (PMID 36389667, 2022). "Interestingly, also malignant cells from certain tumor entities, in particular lymphomas and leukemias, express LILRB1." (PMID 37781391, 2023). "Of note, LILRB1 was found to be displayed by TAM from different types of solid tumors including colon carcinoma, head and neck cancer, non–small cell lung cancer, renal cell carcinoma and by lymphoma associated macrophages." (PMID 37781391, 2023). "Moreover, LILRB1 expressed by lymphoma cells sensitized these cells to lysis by certain γδ T cells, presumably by co-stimulation of the effector cells through ligation of HLA class I on γδ T cells." (PMID 37781391, 2023). "LILRB1-IgGσ revealed the potential also to enhance ADCP of other lymphoma cell lines." (PMID 36389667, 2022). "LILRB1 blockade complemented CD47 inhibition and thus a dual checkpoint blockade of CD47-SIRPα and LILRB1-HLA class I interactions may have the potential to improve antibody therapy of lymphomas further by enhancing ADCP by macrophages." (PMID 36389667, 2022). "As demonstrated here, the blockade of LILRB1 in addition to CD47 may offer a possibility further enhancing rituximab-mediated ADCP of lymphoma cells." (PMID 36389667, 2022). "LILRB1 blockade may be also effective against leukemias and lymphomas." (PMID 37781391, 2023). "In lymphoma models resistant to rituximab (RTX), an anti-CD20 antibody, LILRB1 levels tended to increase, while CD20 was downregulated, and CD22 and CD19 remained largely unchanged." (PMID 40186066, 2025). "Regarding the ‘Don ́t Eat Me!’ function described for HLA class I molecules by interaction with the inhibitory receptor LILRB1, we hypothesized that their expression interfered with ADCP of lymphoma cells and contributed to the observed differences." (PMID 36389667, 2022). "LILRB1-IgGσ promoted serial engulfment of lymphoma cells and potentiated ADCP by non-polarized M0 as well as polarized M1 and M2 macrophages, but required CD47 co-blockade and the presence of the CD20 antibody." (PMID 36389667, 2022). "Thus, dual checkpoint blockade of CD47 and LILRB1 may be promising to improve antibody therapy of CLL and lymphomas through enhancing ADCP by macrophages." (PMID 36389667, 2022). "LILRB1 (also known as CD85J, ILT2, LIR1, and MIR7) and LILRB3 (CD85A, ILT5, LIR3, and HL9) are widely expressed on malignant cells of hematologic malignancies, such as AML, B cell leukemia/lymphoma, and T cell leukemia, where they intrinsically promote tumor progression." (PMID 31186046, 2019).
pancreatic cancer (4 papers, 2021 to 2023). "According to several researches, LILRB1 is essential for promoting tumor growth and metastasis, such as in breast, gastric and pancreatic cancers." (PMID 37142967, 2023). "This study found SIRPα, LILRB1, and SIGLEC-10 to be increased in pancreatic cancer tissues." (PMID 34778091, 2021).
systemic lupus erythematosus (4 papers, 2022 to 2025). An autoimmune multi-organ disease typically associated with vasculopathy and autoantibody production. "Reduced expression or impaired function of LILRB1 and LILRB2 have been associated with inflammatory autoimmune conditions such as rheumatoid or psoriatic arthritis and systemic lupus erythematosus." (PMID 39691709, 2024). "Notably, the LILRB1 missense variant c.479G>A (p.G160E) was associated with familial autoimmune disorders including Graves' disease, Hashimoto's thyroiditis, and systemic lupus erythematosus (SLE)." (PMID 40860159, 2025). "Examination of peripheral blood mononuclear cells (PBMC) from systemic lupus erythematosus (SLE) patients has revealed reduced expression of LILRB1 on CD4+ and CD8+ T cells, B cells and DCs, with LILRB1 on these cells demonstrating a diminished inhibitory function compared to healthy donors." (PMID 38022598, 2023).
T cell lymphomas (4 papers, 2015 to 2024). "For example, LILRB1 expression protected cutaneous T-cell lymphoma cells from CD3/TCR activation induced cell death, while in malignant B cells LILRB1 engagement dampened tumor cell proliferation and induced cell cycle blockade." (PMID 37781391, 2023). "Interestingly, LILRB1 expressing cells from 1 Sezary Syndrome patient were less susceptible to CD3/TCR-dependent activation-induced cell death, an anti-oncogenic role of TCR also noted in adult T-cell lymphoma patients." (PMID 39696628, 2024). "T-cell malignancies have been documented to express HLA-G and LILRB1, including in primary cutaneous CD8 + and CD56 + T-cell lymphomas and peripheral circulating Sézary cells." (PMID 39696628, 2024).
Autoimmunity (3 papers, 2022 to 2025). The occurrence of an immune reaction against the organism's own cells or tissues. "This pathway also includes the ER aminopeptidase encoded by ERAP2 and the leukocyte immunoglobulin-like receptor subfamily B member 1 (LILRB1) gene, a gene associated with familiar autoimmunity." (PMID 40883722, 2025). "In summary, this study is the first to implicate LILRB1 as a new monogenic disease gene for autoimmunity." (PMID 36104364, 2022). "This study, for the first time, implicates LILRB1 as a new disease gene for autoimmunity." (PMID 36104364, 2022).
clear cell renal cell carcinoma (3 papers, 2021 to 2025). "LILRA1, LILRA2, LILRA5, LILRB1, LILRB2, and LILRB3 are differentially expressed across several cancer types, including lung squamous cell carcinoma, lung adenocarcinoma, papillary renal cell carcinoma, and clear cell renal cell carcinoma, suggesting a potential pan-cancer role for LILR family genes." (PMID 40843931, 2025).
glioblastoma (3 papers, 2023 to 2025). The most malignant astrocytic tumor (WHO grade IV). "Similarly, enhanced NK cell cytotoxicity against glioblastoma cells was observed in vitro when LILRB1 was blocked." (PMID 37781391, 2023). "Within the glioblastoma TME, LILRB1 was predominantly expressed on NK cells, where co-culture with tumor cells induced its expression and impaired NK cell cytotoxicity." (PMID 40860159, 2025).
B-cell lymphoma (2 papers, 2024 to 2025). "We observed stable LILRB1 expression in B-ALL and B-cell non-Hodgkin lymphoma (B-NHL), even after CD20/CD19-based immunotherapies." (PMID 40186066, 2025).
co-infection (2 papers, 2018 to 2025). "Interestingly, both LILRB1 and LILRB2 were markedly upregulated in response to HCMV, especially after TB40 infection, with elevated expression already evident in TB40 single infection and further amplified during co-infection." (PMID 40980889, 2025).
cutaneous T cell lymphoma (2 papers, 2020 to 2024). "In a cell line derived from a cutaneous T-cell lymphoma (CTCL), LILRB1 was found to constitutively associate with SHP-1 phosphatase, a negative regulator of TCR signaling." (PMID 39696628, 2024).
dengue (2 papers, 2016 to 2019). "Antibody opsonized dengue has recently been shown to co-ligate the inhibitory receptor LILRB1 when engaged by FcγR, leading to inhibition of FcγR signaling and indicating that LILRB1 may play a role in antibody-dependent dengue." (PMID 27504110, 2016). "In addition, CD19+CD27− naïve B cells isolated from dengue patients were refractory to TLR/anti-IgM stimulation in vitro, which correlated to the increased expression of inhibitory Fcγ receptors (FcγR) CD32 and LILRB1 on CD19+CD27− naïve B cells from DENV-infected patients." (PMID 31736948, 2019).
leukemia (2 papers, 2023 to 2025). A malignant (clonal) hematologic disorder, involving hematopoietic stem cells and characterized by the presence of primitive or atypical myeloid or lymphoid cells in the bone marrow and the blood. "Thus, masking of LILRB1 enhanced NK cell cytotoxicity against HLA class I-expressing leukemia cells, in particular when KIR or NKG2A were blocked simultaneously." (PMID 37781391, 2023).